HOTAIR (HOX transcript antisense RNA)
Diseases named in the same sentence as HOTAIR in open-access papers (continued):
Sharing a sentence is not in itself a finding about the gene and the disease.
breast cancer (continued). "Similarly, the expression level of HOTAIR is positively correlated with hazard risk, which implies HOTAIR could be an oncogenic lncRNA in breast cancer." (PMID 34082714, 2021). "Given that HOTAIR rs12826786 C>T polymorphism leads to higher expression of HOTAIR thus, the presence of the homozygous variant allele might be a predisposing or susceptibility factor for the development of breast cancer through enhancement of proliferation." (PMID 33584136, 2021). "It was implicated that HOTAIR could mimic oncogenic behaviour in several breast cancer patients, leading to the aberration of several molecular pathways, towards the malignant cell proliferation, invasion, EMT, metastasis as well as resistance against different therapeutic agents." (PMID 32245498, 2020). "Therefore, understanding the biological roles of HOTAIR may help us to recruit this lncRNA as a diagnostic or predictive biomarker in breast cancer." (PMID 29423075, 2018). "Other genes present in the cross-cancer CIMP signature such as HOTAIR, which is known to reprogram the chromatin state and is associated with breast cancer metastasis, might on the contrary be repressed in CIMP tumors and be linked with a better prognosis for breast cancer patients." (PMID 26463173, 2015). "Despite these findings, further research is needed to clarify HOTAIR’s roles in the initiation, progression, and metastasis of breast cancer." (PMID 39997609, 2025). "CAFs-derived TGF-β drives EMT and enhances fibronectin, vimentin, MMP-2/9, SNAIL, and TWIST expression, promoting breast cancer cell motility, drug resistance, and stemness via upregulation of lncRNA HOTAIR, silencing tumor suppressor genes." (PMID 40230452, 2025). "Another study comparing plasma from breast cancer patients to healthy controls found elevated levels of lincRNAs H19, HOTAIR, and RP11-445H22.4." (PMID 39997609, 2025). "Among them, the HGF/c-MET pathway is closely related to cancer metastasis and can promote breast cancer resistance to tamoxifen through the EZH2/HOTAIR-MIR-141/200A feedback signaling pathway." (PMID 40860340, 2025). "Among the numerous lncRNAs implicated in drug resistance, MALAT1, UCA1, CYTOR, and HOTAIR have emerged as crucial oncogenes, and GAS5 is a well‐known lncRNA that acts as a tumor suppressor in breast cancer." (PMID 41031251, 2025). "MiR-20a-5p, which interacts with HOTAIR, has been evaluated as a biomarker in cervical cancer, breast cancer, and leukemia." (PMID 40686703, 2025). "Numerous studies have identified upregulated lincRNAs, including BREAST CANCERR4, linc-ROR, and HOX transcript antisense RNA (HOTAIR), as the key breast cancer invasion and metastasis facilitators." (PMID 39997609, 2025). "Taken together, by acting as a scaffold and interacting with the PRC2 complex, the upregulation of HOTAIR in NK cells from breast cancer patients can negatively affect the antitumor immunity of NK cells in breast cancer patients." (PMID 40781182, 2025). "In the literature, both HMGA2 and HOTAIR have been revealed to be effective in breast cancer development, progression, and metastasis." (PMID 40686703, 2025). "Extensive research has focused on investigating HOTAIR in breast cancer, a lncRNA that regulates the HOXC gene cluster and influences gene expression in various biological processes, including cancer progression." (PMID 39858015, 2025). "Early investigations revealed that HOTAIR promotes breast cancer metastasis and is highly expressed in metastatic breast cancer tissues." (PMID 39997609, 2025). "Another well‐characterized oncogenic lncRNA, HOTAIR, functions as a molecular scaffold for chromatin‐modifying complexes and is known to promote breast cancer progression by inhibiting tumor suppressor miRNAs while activating pro‐oncogenic miRNAs." (PMID 41031251, 2025). "We found that the expression of HOTAIR was higher in breast cancer patients than in controls (p value: 0.025), which is consistent with previous literature." (PMID 40686703, 2025).
breast cancer (continued). "For example, in breast cancer, HOTAIR has been shown to upregulate certain oncogenes by sequestering miRNAs,18 thus promoting tumor cell proliferation and metastasis." (PMID 40235720, 2025). "In glioblastoma, lncRNAs like MALAT1 and HOTAIR contribute to tumor growth and resistance through similar immunosuppressive mechanisms within the tumor microenvironments seen in breast cancer." (PMID 41031251, 2025). "The correlation between HOTAIR and ERβ, along with subsequent downstream miRNA molecules, such as miR‐138, miR‐204, miR‐217 complex and miR‐200c, in breast cancer, remains to be investigated." (PMID 39285617, 2025). "HOTAIR is a lncRNA that is upregulated in breast cancer and promotes tumour growth and metastasis by repressing the expression of tumour suppressor genes." (PMID 39912983, 2025). "Breast cancer cells have shown a statistically significant in vitro upregulation of HOTAIR, when growing in substrates enriched in laminin, suggesting the relation between this lncRNA and ECM composition." (PMID 39285617, 2025). "Prominent examples of the impact of m6A modifications on lncRNA function include regulation of Xist in gene silencing and the role of HOTAIR in breast cancer." (PMID 40559622, 2025). "The long non-coding RNA HOTAIR plays a crucial role in regulating cancer cell proliferation and invasion in breast cancer." (PMID 41294885, 2025). "HOTAIR has been demonstrated to modify the chromatin state during tumor metastasis and is increased in metastatic breast carcinomas, leading to a modified distribution of PRC2 activity from embryonic fibroblasts to breast epithelial cells." (PMID 39971705, 2025). "The role of HOTAIR in tumour behaviour and its potential as a prognostic biomarker is extensively described in various types of cancer such as: 1) in breast cancer (BC), HOTAIR expression can be induced by estrogen, promoting cell proliferation." (PMID 38887279, 2024). "By also interacting with chromatin, HOTAIR is involved in breast cancer migration and promotes tumor metastasis via altering chromatin status." (PMID 38095719, 2024). "Studies have shown that HOTAIR-mediated direct inhibition of miR-7 in breast cancer stem cells can upregulate SETDB1 and inhibit E-cadherin, thus favoring EMT." (PMID 39583200, 2024). "Recent studies have revealed that lncRNA HOTAIR is upregulated in tamoxifen-resistant breast cancer cells compared to primary breast cancer cells, which contributes to enhanced ER signaling, even in the absence of estrogen." (PMID 39439957, 2024). "In CSCs enriched from breast cancer cells, expression of HOTAIR is essential for migration, invasion, and self-renewal potential." (PMID 39170516, 2024). "The potential of ASOs is illustrated by their effectiveness against HOTAIR and MALAT1, lncRNAs implicated in breast cancer metastasis and oncogenesis." (PMID 38505593, 2024). "Compared with normal tissues, HOTAIR expression level was upregulated in various tumors, including colorectal cancer, breast cancer, brain cancer, kidney cancer, lung cancer, pancreatic cancer, skin cancer, stomach cancer and uterus cancer (P < 0.05)." (PMID 38696320, 2024). "For instance, the lncRNA HOTAIR, which is overexpressed in breast cancer, can change gene expression through alterations in chromosome structure." (PMID 38189818, 2024). "In breast cancer, upregulation of HOTAIR has been shown to downregulate the expression of miR‐454‐3p, thereby promoting tumour cell proliferation and invasion." (PMID 39347925, 2024). "For instance, HOTAIR has been found to be significantly elevated in the serum of breast cancer patients compared to healthy individuals, suggesting its potential as a diagnostic biomarker." (PMID 38505593, 2024). "The knockout of HOTAIR has been demonstrated to reduce drug resistance in breast cancer cells to doxorubicin." (PMID 39795985, 2024). "HOTAIR, which prompted the proliferation and migration of breast cancer cells, is transcriptionally activated by estradiol." (PMID 38688909, 2024).
breast cancer (continued). "HOTAIR affected and blocked the growth, metastasis, and apoptosis of breast cancer cells through the miR-20a-5p/HMGA2 axis." (PMID 37404755, 2023). "Meredith and co-workers reported that hnRNPA2/B1 knockdown negatively regulates HOTAIR-dependent invasion of breast cancer cells." (PMID 37308974, 2023). "Firstly, we examined HOTAIR expression in breast cancer tissues by the RT-qPCR assay and examined HOTAIR protein expression via immunocytochemistry, to chemical assay, and Western blot." (PMID 36816362, 2023). "In breast cancer tissue and cells, the lncRNA HOTAIR was upregulated, and its knockdown inhibited cell propagation, metastasis and facilitated cell apoptosis." (PMID 37143733, 2023). "Collectively, our findings contribute to the growing body of evidence supporting a correlation between ESR1 and HOTAIR in breast cancer pathogenesis." (PMID 38114755, 2023). "Circulating levels of HOTAIR and miR-130a hold promise as non-invasive biomarkers for predicting the pathological features of breast cancer patients." (PMID 38114755, 2023). "High expression levels of HOTAIR in many cancers, such as lung cancer, cervical cancer, breast cancer, gliomas, prostate cancer, ovarian cancer, and oral cancer, have been reported in many studies." (PMID 36924407, 2023). "In conclusion, this study revealed a positive correlation between HOTAIR and miR-1246 expression and exerts an oncogenic impact in patients with breast cancer, and reported a decline in IL-39 levels in patients with breast cancer." (PMID 36865390, 2023). "They observed that the serum expression level of HOTAIR was significantly higher in the breast cancer patients compared to the fibroadenoma patients and the control subjects." (PMID 37776415, 2023). "The expression levels of HOTAIR are elevated in a variety of tumors, including breast cancer, lung cancer, GC, hepatocellular carcinoma and glioma." (PMID 36765563, 2023). "In primary and metastatic breast cancer cells, HOTAIR expression is up to hundreds-fold higher than in normal breast epithelia." (PMID 37990044, 2023). "In breast cancer, HOTAIR is critical to tumor progression and can directly or indirectly regulate key cellular processes such as cell proliferation, cell invasion, EMT, self-renewal, metastasis, and drug resistance." (PMID 36924407, 2023). "Compared to matched healthy females, breast cancer patients had a higher mean in relative levels of serum miR-1246 and HOTAIR." (PMID 36865390, 2023). "Particularly, mutagenesis of the adenosine to uracil demonstrated that the residue A783 is required for HOTAIR function in promoting proliferation and invasion of breast cancer cells." (PMID 37308974, 2023). "The differential expression fold of miR-1246 and HOTAIR revealed a strong positive correlation among breast cancer patients." (PMID 36865390, 2023). "A Smad-mediated molecular mechanism of TGF-β1-induced HOTAIR regulation was reported by Ren and Colleagues in breast cancer cells." (PMID 37308974, 2023). "Sorensen and colleagues evaluated the potential role of lncRNAs in breast cancer prognosis and identified HOTAIR as an independent prognostic marker of metastases." (PMID 37143733, 2023). "Previous studies have examined the connection between HOTAIR SNPs rs4759314 and rs920778 for breast cancer (BC), getting variable results in multiple ethnicities." (PMID 37776415, 2023). "Recently, HOTAIR rs920778 polymorphisms with higher survival rates were reported in CRC patients from South Korea and in breast cancer patients in southeast Iran." (PMID 36980864, 2023). "Therefore, over the past decade, HOTAIR has been recognized as a critical regulator of mechanisms associated with breast cancer (BC) progression and understanding the cancer-facilitating mechanisms of HOTAIR could assist in developing novel treatment strategies for BC." (PMID 36997931, 2023). "HOTAIR is often found upregulated in several cancers including breast cancer, prostate cancer, and pancreatic tumors." (PMID 38132140, 2023).
breast cancer (continued). "Gupta and Coworkers successively reported that HOTAIR overexpression in epithelial breast cancer cells induces a genome-wide retargeting of PRC2 (and H3K27me3)." (PMID 37308974, 2023). "In breast cancer, HOTAIR expression is augmented in primary breast tumors and metastases, and the HOTAIR expression level in primary tumors is a powerful predictor of metastases and death." (PMID 36924407, 2023). "Currently, several examples of lncRNAs have been described as potential clinical biomarkers for predicting response to therapy or for prognosis in breast cancer, such as HOTAIR, H19, and DSCAM-AS1." (PMID 37108589, 2023). "With respect to HOTAIR, the role of m6A in the specific control of its function has been recently highlighted by Porman and Colleagues in breast cancer cells." (PMID 37308974, 2023). "In this study, we demonstrate a significant correlation between the expression levels of ESR1, HOTAIR, and miR-130a in the serum of breast cancer patients." (PMID 38114755, 2023). "siRNAs targeting BC-related lncRNAs (such as HOTAIR) have been shown to inhibit breast cancer growth and invasion." (PMID 35865634, 2022). "Altogether, our results suggest that the increased metastatic potential of HOTAIR overexpressing breast cancer cells requires ongoing HOTAIR activity and is abrogated by silencing HOTAIR." (PMID 36579891, 2022). "A previous study showed that HOTAIR is strongly involved in the initiation, metastasis, and drug resistance of breast cancer." (PMID 36361470, 2022). "The inhibition of HOTAIR impaired cell migration and invasion by interacting with miR-601 in breast cancer." (PMID 36613528, 2022). "To sum up, we constructed a GI-related prognostic risk model comprising six lncRNAs (U62317.4, MAPT-AS1, AC115837.2, EGOT, SEMA3B-AS1, and HOTAIR) in breast cancer." (PMID 35990656, 2022). "In another study of breast cancer cell lines, the role of HOTAIR in the regulation of cellular radiosensitivity has been reported through the sponging of miR-449b-5p." (PMID 36457703, 2022). "In breast cancer cell lines, knockdown of HOTAIR increases cellular radiosensitivity and promotes DNA damage and cell-cycle arrest by suppression of miR-218." (PMID 36457703, 2022). "This study shows that the lncRNA HOTAIR represses or activates genes, depending on a single m6A modification, to affect breast cancer cell biology." (PMID 36441764, 2022). "The inhibition of HOTAIR reversed the promotion of breast cancer cell progression induced by miR-203 down-expression." (PMID 36233075, 2022). "The HOTAIR-rtTA-PyMT transgenic mouse generated in this paper provides a model to analyze the functional role of human HOTAIR in vivo within the context of breast cancer metastasis." (PMID 36579891, 2022). "Interaction of EZH2 with HOTAIR: The EZH2 Polycomb complex can interact with the long non-coding RNA HOTAIR, which is highly expressed in breast cancer metastases, and a small molecular weight inhibitor of this interaction has been developed." (PMID 35406676, 2022). "HOTAIR is highly expressed in breast cancer metastasis, inducing the overexpression of the HER2 oncogene through sequestration of miR-331-3p." (PMID 35626715, 2022). "According to the coefficient of each lncRNA, we found that HOTAIR and AC115837.2 increased the risk score of a breast cancer patient, while U62317.4, EGOT, MAPT-AS1, and SEMA3B-AS1 tended to decrease the score." (PMID 35990656, 2022). "The overexpression of HOTAIR can activate estrogen receptor transcription, inducing breast cancer drug-resistant and promoting cancer cell proliferation." (PMID 36233075, 2022). "To identify HOTAIR-interacting proteins in an unbiased way in whole cell lysates, we applied ChIRP-MS on the endogenous HOTAIR in MCF7 breast cancer cells, a commonly used cell line in HOTAIR research." (PMID 35087108, 2022).
breast cancer (continued). "Mapping m6A in breast cancer cell lines, we identify multiple m6A sites on HOTAIR, with 1 single consistently methylated site (A783) that is critical for HOTAIR-driven proliferation and invasion of triple-negative breast cancer (TNBC) cells." (PMID 36441764, 2022). "The results indicated that MAPT-AS1, EGOT, and SEMA3B-AS1 were downregulated while the expression of HOTAIR was increased in breast cancer cell lines, which were consistent with the predicted results." (PMID 35990656, 2022). "While it is evident that m6A modification of A783 in HOTAIR is important for mediating its effects in breast cancer, other m6A sites within HOTAIR appear to play a role in enabling its high expression levels, potentially through transcript stabilization." (PMID 36441764, 2022). "To evaluate m6A methylation of HOTAIR in relevant breast cancer cells, we performed m6A RNA immunoprecipitation (meRIP) qRT-PCR in MCF-7 cells, which express low levels of endogenous HOTAIR." (PMID 36441764, 2022). "Suppression of IRF1 expression by IRF1 siRNAs (TCanti-IRF1, stimulated HOTAIR expression and reduced the anticancer effects of Dp, signifying that Dp interferes with the regulation of Akt/IRF1/HOTAIR signaling pathway in breast cancer." (PMID 35369062, 2022). "Previous reports demonstrated that HOTAIR expression is dysregulated in various types of cancers, including breast cancer, liver cancer, and lung cancer." (PMID 35798695, 2022). "In breast cancer (BC), HOTAIR upregulates HMGA2 expression by competitively binding to miR-20a-5p, resulting in cell growth, metastasis, and apoptosis." (PMID 35813070, 2022). "As our initial validation demonstrates, knockdown of HOTAIR inhibited the proliferation, invasion, and migration of breast cancer cells." (PMID 36233075, 2022). "The levels of HOTAIR in metastatic breast cancer tissues were higher than normal breast epithelium and primary breast cancer foci, and high HOTAIR expression was associated with poorer prognosis in patients and with metastasis in the course of the disease." (PMID 36686701, 2022). "To further study the function and mechanism of HOTAIR in promoting breast cancer progression, we engineered the inducible HOTAIR (iHOT) genetic system into a breast cancer model background." (PMID 36579891, 2022). "The expression of HOTAIR is very high in breast cancer metastases and already a small molecular weight inhibitor of the interaction of the EZH2 complex with the 5′ end of HOTAIR has been developed (and see Polycomb section)." (PMID 35406676, 2022). "As individual mice are variable in tumor progression, we isolated breast cancer cells from the primary tumors of iHOT-PyMT mice (abbreviated as iHOT+ cells) in order to gain further mechanistic insight into the functionality of HOTAIR." (PMID 36579891, 2022). "The results showed that, compared with normal tissues, HOTAIR was highly expressed in breast cancer." (PMID 36233075, 2022). "Mechanistically, the oncogenic role of HOTAIR in breast cancer was mediated by the sponging of miR-601 and subsequently regulated ZEB1 expression." (PMID 36613528, 2022). "Additional findings from xenograft breast cancer model identified upregulation of lncRNA HOTAIR and chondroitin sulfotransferase CHST15 (GalNAc4S-6ST)." (PMID 36685962, 2022). "It was shown that HOTAIR was upregulated in breast cancer tissues, and its knockdown inhibited the proliferation, migration, invasion, and activity of the Akt signaling of breast cancer cells." (PMID 35328609, 2022). "Using the well-characterized MMTV-PyMT system for endogenous breast cancer development, we confirmed that the induced overexpression of HOTAIR facilitates breast cancer metastasis to the lung and an ongoing dependency on HOTAIR for this phenotype." (PMID 36579891, 2022). "Overexpression of serum exosomal or serum circulating HOTAIR has been also repeatedly evidenced and found correlated with poor survival and poor response to chemotherapy in breast cancer patients." (PMID 35076579, 2022).